REV3L (REV3 like, DNA directed polymerase zeta catalytic subunit)
Diseases named in the same sentence as REV3L in open-access papers (continued):
Sharing a sentence is not in itself a finding about the gene and the disease.
Moebius syndrome (1 paper, 2021). Moebius syndrome is a very rare congenital cranial dysinnervation disorder characterized by complete or incomplete facial paralysis in association with bilateral palsy of the abducens nerve causing impairment of ocular abduction. "Additionally, three individuals were reported with de novo, heterozygous missense variants in REV3L (two with Moebius syndrome and one with isolated CFP without a defect in ocular motility), suggesting that HCFP and Moebius syndrome may be allelic disorders." (PMID 33827624, 2021).
Poland syndrome (1 paper, 2022). Poland syndrome is marked by a unilateral absence or hypoplasia of the pectoralis major muscle (most frequently involving the sternocostal portion), and a variable degree of ipsilateral hand anomalies, including symbrachydactyly. "Of the candidate genes thus far implicated in Poland syndrome, only REV3L (chromosomal locus 6q21-22.1) appears to be of interest here." (PMID 36581828, 2022). "On this occasion, the larger study cohort of MBS yielded 3 de novo PLXND1 gene mutations and 3 additional de novo mutations in the gene REV3L one of whom exhibited incidental features of Poland’s syndrome." (PMID 36581828, 2022).
psoriasis (1 paper, 2023). An autoimmune condition characterized by red, well-delineated plaques with silvery scales that are usually on the extensor surfaces and scalp. "Furthermore, REV3L has recently been identified as a candidate for gene therapy for psoriasis and PsA using a genetics-dependent drug target prioritization approach." (PMID 37662940, 2023).
rheumatoid arthritis (1 paper, 2023). A chronic, systemic autoimmune disorder characterized by inflammation in the synovial membranes and articular surfaces. "Single nucleotide polymorphisms (SNPs) in the intergenic region between REV3L and the neighboring gene KIAA1919 are associated with the development of rheumatoid arthritis (RA) in black South Africans." (PMID 37662940, 2023).
Thrombocytopenia (1 paper, 2020). A reduction in the number of circulating thrombocytes. "Furthermore, REV3L rs462779 showed a slight association with severe toxicity (thrombocytopenia) in NSCLC patients treated with platinum-based chemotherapy." (PMID 32489453, 2020).
type 2 diabetes (1 paper, 2017). "Nevertheless, two SNPs (FADS1, REV3L) which were associated with metabolite traits were significant in bigger consortia for type 2 diabetes, such as DIAGRAM2 or GoT2D14." (PMID 28729637, 2017). "In summary, we identified a novel metabolite locus (MOGAT2) in single variant analyses and four genes (GFRAL, BIN1, TFRC, OR51Q1) within gene-based tests and could show that two previously known mGWAS loci (FADS1 and REV3L) might be relevant for the risk of type 2 diabetes." (PMID 28729637, 2017).
uterine cancer (1 paper, 2020). Primary or metastatic malignant neoplasm involving the uterine corpus and/or the cervix. "Since mutations in POLE confer increased disease free survival (DFS) in patients with uterine cancer, even in those patients with high-grade tumors, we investigated the prognostic role of POLQ and REV3L mutations in POLE mutant tumors." (PMID 32838755, 2020).
Vertigo (1 paper, 2025). An abnormal sensation of spinning while the body is actually stationary. "Additional SNPs not in LD with rs3777909 that were associated with vertigo at p < 0.05 were also eQTLs/sQTLs for MFSD4B and REV3L." (PMID 40913328, 2025). "For vertigo, rs3777909 (p = 3.1 × 10−5) was an eQTL for MFSD4B in nerve and REV3L in brain tissue, along with three other eQTLs for MFSD4B and four for REV3L associated with vertigo (p < 0.05)." (PMID 40913328, 2025). "For vertigo, rs3777909 (p = 3.14 × 10−5) was an eQTL for MFSD4B in nerve and REV3L in brain tissue, with SNPs not in LD also being eQTLs for these genes and associated with vertigo at p < 0.05, among the top 5% of SNPs with the strongest association with this toxicity." (PMID 40913328, 2025).
cancer (27 papers, 2011 to 2025). A tumor composed of atypical neoplastic, often pleomorphic cells that invade other tissues. "In silico, higher MFSD4B and REV3L expression in cancer cell lines were associated with significantly greater cisplatin sensitivity." (PMID 40913328, 2025). "REV3L encodes the protein representing the catalytic sub-unit of Polζ, and inhibiting REV3L expression enables cancer cells to tolerate DNA damage and stunted growth." (PMID 32457603, 2020). "E + Q and E + Z mutant tumors also displayed significantly higher mutation counts compared to E-only mutant tumors, suggesting a contribution of mutationally altered POLQ or POLZ/REV3L to the overall cancer mutation rates." (PMID 32838755, 2020). "The reversionless 3-like (REV3L) is the catalytic subunit of DNA polymerase ζ, which participates in DNA synthesis, and played a critical role in chemoresistance in a variety of cancers." (PMID 39744159, 2025). "REV3L is highly overexpressed in several cancers and facilitates cancer cell proliferation, metastasis, and insensitivity to cisplatin." (PMID 39749345, 2024). "Our in vitro results indicated that MGMTlow MMRproficient HRdeficient cancer cells with low REV3L mRNA expression are sensitive to the TMZ + ATRi combination." (PMID 34676045, 2021). "Reversionless 3-like (REV3L), the catalytic subunit of DNA polymerase ζ, alters the development and chemoresistance of diverse cancers." (PMID 33817237, 2020). "REV3L has been demonstrated to mediate tumor development and chemosensitivity in diverse cancers, such as NSCLC, ESCC and squamous cell carcinoma of the head and neck." (PMID 33817237, 2020). "Cancers with mutations in POLE and POLQ (E/Q), POLE and POLZ/REV3L (E/Z) and in all 3 polymerases (E/Q/Z) were associated with the highest mutation burden and an excellent prognosis independent of MSI status and tumor stage." (PMID 32838755, 2020). "BRCA2, BLM, ERCC2, RECQL, REV3L and RIF1 were among the most promising candidates, with some of them previously associated with predisposition syndromes to other cancers." (PMID 30871259, 2019). "Disrupted REV3L in cancer cell lines showed the importance of accurately regulated REV3L expression, when its inhibition induced DNA damage and growth arrest in cancer cells, whereas overexpression led to increased spontaneous mutation rates." (PMID 30591675, 2018). "Next, by using of publicly available databases, we evaluated whether the Rev3L mRNA expression levels could predict the cancer patients’ response to cisplatin treatment." (PMID 31189884, 2019). "Importantly, SOX17 transcriptionally down-regulated DNA repair and damage response-related genes including BRCA1, BRCA2, RAD51, KU80 DNAPK, p21, SIRT1, NFAT5 and REV3L in KYSE510 radio-resistant cells to achieve the sensitization effect to anti-cancer treatment." (PMID 30777052, 2019). "Specifically REV3L, the catalytic subunit of pol ζ, is thought to be one of the major components of error-prone TLS and plays a significant role in the chemoresistance of many cancers." (PMID 34676045, 2021).
tumor (22 papers, 2011 to 2026). "Genetic variations in REV3L have been reported that it was associated with tumor risk or survival in multiple kinds of tumors." (PMID 32489453, 2020). "Several mutations in miR binding sites on the 3’-UTR region of REV3L have been previously reported, and these mutations prevent many tumor suppressing microRNAs binding to and downregulating REV3L." (PMID 29435169, 2018). "However, why mutations in POLQ and REV3L preferentially increase tumor mutation frequencies remains elusive." (PMID 32838755, 2020). "One consequence of the genome protective function of pol ζ is that Rev3l is a suppressor of spontaneous tumor formation." (PMID 30046772, 2018). "Mice conditionally deleting Rev3l in a fraction of hematopoietic cells or in basal skin keratinocytes are viable, but exhibit enhanced tumor incidence, as a consequence of the chromosomal instability of Rev3l-null cells." (PMID 26727495, 2016). "Specifically, expression of POLK, POLQ and REV3L increased in the tumor cells while that of POLH, POLK, POLQ and REV3L decreased in the normal controls." (PMID 24260050, 2013). "qPCR results revealed that the mRNA quantities of POLH, POLK, POLQ and REV3L in XP-V tumor cells were lower than those of the controls; however, the expression of POLI was higher in the XP-V tumor cells in the absence of UV irradiation (P<0.05)." (PMID 24260050, 2013). "An interesting network component includes miR-145, the TF MEIS1 (a development and neoplasia gene) and the REV3L gene (the catalytic subunit of DNA polymerase zeta, involved in DNA repair and genome stability), all down-regulated in NTM progression." (PMID 23987127, 2013). "REV3L is mutated or deleted in a subset of solid tumors, suggesting that TMZ + ATRi might be an attractive combination for an array of tumor types." (PMID 34676045, 2021). "The relevance of REV3L mRNA expression in identifying TMZ + ATRi sensitive models is underscored by the significant tumor growth delay and improved survival of mice bearing low-REV3L compared to higher-REV3L TMZ-resistant PDXs, despite those having some response to TMZ as a single agent." (PMID 34676045, 2021). "Second, we independently confirmed all three REV3L mutations using Sanger sequencing in cisplatin-treated tumor samples but not in the cisplatin-naive samples from the same patients." (PMID 26790612, 2016). "Upon UV irradiation, all these genes were expressed at higher levels in the tumor cells than in the control cells (P<0.05), with the exception of REV3L, which exhibited similar expression levels in the XP-V tumor cells and one of the normal controls (sample UV2)." (PMID 24260050, 2013). "In the present study, low expression of POLH, POLK and REV3L was observed in the XP-V tumor cells." (PMID 24260050, 2013). "We tested whether tumor mutation burden, patient outcome (disease-free survival) and immune cell infiltration measured by ESTIMATE can be attributed to mutations in POLQ and POLZ/REV3L." (PMID 32838755, 2020). "Moreover, the levels of lnc-PICSAR, REV3L mRNA and REV3L protein were drastically reduced, and miR-485-5p was drastically increased in tumor tissues from sh-lnc-PICSAR groups compared to sh-NC groups, as analyzed by the qRT-PCR assay, western blot assay and IHC assay." (PMID 33817237, 2020). "When compared the top 20% of VEGFA expressing tumor samples to the bottom 20% expressing tumors and found that POLH goes up 1.69-fold (FDR 1 × 10−10), POLI goes up 2.06-fold (FDR 1.3 × 10−15) and REV3L goes up 1.62-fold (FDR 3.8 × 10−6)." (PMID 39468223, 2025). "REV3L encodes a catalytic subunit of an error-prone DNA polymerase ζ, whose involvement in both double strand break (DSB) repair and translesion synthesis (TLS) pathways may explain why it is the only known specialized DNA polymerase reducing spontaneous tumor development." (PMID 30591675, 2018).
tumor (continued). "Furthermore, defects in DNA repair and damage response genes such as RAD51, KU80 SIRT1, NFAT5, and REV3L, or ESCC tumor cells expressed higher CLDN4 to harbor stem-like properties are also the potential CCRT resistance mechanisms." (PMID 35457185, 2022). "Both REV3L and REV7 were reported to regulate cell proliferation, apoptosis, cycle, invasion, and angiogenesis, and their abnormal regulation and functioning are closely related to tumor development." (PMID 34281455, 2021).
REV3L also shares sentences with these, for which no sentence is quoted: B cell lymphomas (3 papers); gastric cancer (3); Anaemia (2); lung adenocarcinoma (2); autoimmune disease (1); brain glioma (1); breast tumor (1); colorectal adenocarcinoma (1); colorectal cancer (1); esophageal squamous cell carcinoma (1); Facial palsy (1); head and neck cancer (1); head and neck tumors (1); infection (1); insomnia (1); leukemia (1); lung squamous cell carcinoma (1); neuropathy (1); neurotoxicity (1); osteosarcoma (1); Paralysis (1); prostate carcinoma (1); stomach cancer (1); Thyroid Carcinoma (1); uterine corpus endometrial carcinoma (1).